S1PR1 (sphingosine-1-phosphate receptor 1)
Diseases named in the same sentence as S1PR1 in open-access papers (continued):
Sharing a sentence is not in itself a finding about the gene and the disease.
tumor (continued). "S1P signaled through S1PR1 to promote pro-inflammatory cytokine expression and macrophage infiltration, favoring tumor progression and the induction of the premetastatic niche in lungs." (PMID 35163211, 2022). "S1PR1 was the first S1P receptor identified in human umbilical vein ECs (HUVECs) and was recently reported to have an important role in tumour angiogenesis, attracting increasing attention as a new antivascular target." (PMID 36068200, 2022). "Early studies suggested that BAF312 inhibits tumor growth and reduces angiogenesis via downregulating S1PR1 expression." (PMID 34059068, 2021). "Reduced uptake of 99mTc-HYNIC-S1PR1mAb in SK-HEP-1 was observed in tumor-bearing nude mice pretreated with fingolimod, which binds competitively to the receptors, especially S1PR1." (PMID 34484174, 2021). "Inhibition of S1PR1 can destroy tumor blood vessels in xenograft tumor models and ultimately inhibit tumor growth." (PMID 34484174, 2021). "The inhibition of S1PR1 expression down-regulates STAT3 function leading to halting in tumor cell survival and invasion." (PMID 33920887, 2021). "Given the complexity of immune cell infiltration and tumor purity, the exact expression and inhibitory effect of S1PR1 in bulky bladder cancer tumor still needs to be validated." (PMID 34503284, 2021). "The TCGA database shows that S1PR1 expression is significantly higher in normal tissues than in tumor tissues for most cancers." (PMID 34503284, 2021). "In vivo studies have shown that S1PR1 inhibitors can reduce the vascular stability of Lewis lung cancer and inhibit angiogenesis and tumor growth." (PMID 34484174, 2021). "Contrary to the pro-tumor roles of S1PR1, S1PR2, and S1PR3, S1PR5 was claimed to exert inhibitory effects on the proliferation and migration of esophageal cancer via the Ras/ERK, PI3K/Rac and Rho/ROCK signaling pathways." (PMID 34831211, 2021). "The combination of S1PR1 antagonist and chemotherapy drugs can be used as a new strategy for tumor treatment." (PMID 34484174, 2021). "Overall, S1PR1 promotes tumor growth by increasing VEGFR2 expression on the surface of endothelial cells, and thus increasing VEGFR2-mediated angiogenic signaling." (PMID 34690821, 2021). "The blockade of S1PR1/3 by VPC23019 suppresses tumor growth, angiogenesis, and angiogenic factor expression in ovarian cancer cells." (PMID 33920887, 2021). "S1PR1 enhances the migratory ability of the proliferating cells in a kidney-derived tumor cell line wiT49." (PMID 35201458, 2021). "As aberrant IL‐6–JAK–STAT3 signaling is an important mechanism for cancer initiation, development, and progression, S1P/S1PR1 signaling accelerates tumor growth and metastasis via an IL‐6/JAK2‐mediated persistent activation of STAT3." (PMID 34289244, 2021). "S1PR1 is involved in, among many processes, promotion of proliferation and invasion of tumor cells and the formation of new blood vessels." (PMID 34484174, 2021). "In BC, sphingosine kinase 1, which is necessary for the generation of S1P and its receptor S1PR1 can induce the release of proinflammatory cytokines, macrophage infiltration, and tumor progression." (PMID 34777473, 2021). "Obesity and high-fat diet are the main cause for increased expression of the S1P and SPHK1, and targeting the SPHK1/S1P/S1PR1 decreases key proinflammatory cytokines, macrophage infiltration, and tumor progression." (PMID 34283088, 2021). "The SMYD3-overexpressing and S1PR1-overexpressing groups showed significantly increased tumor growth compared to the control group." (PMID 34301921, 2021). "All these results suggest that S1PR1 affects tumor growth and vascular formation through the S1PR1/P-STAT3/VEGFA pathway." (PMID 34059068, 2021). "For the first time, our work confirms that S1PR1 affects tumor growth and angiogenesis via the S1PR1/P-STAT3/VEGFA axis." (PMID 34059068, 2021).
tumor (continued). "Patients with bladder cancer were found to have higher levels of S1PR1 and immunosuppressive cytokine secretion (TGF-β, IL-10), along with more circulating and tumor-infiltrating regulatory T cells, which is associated with poor patient outcomes." (PMID 34069611, 2021). "Gene expression analysis of the TCGA database provided by Timer 2.0 showed that S1PR1 expression was significantly higher in normal tissue than in tumor tissue in most cancers, including BLCA." (PMID 34503284, 2021). "S1PR1 has played an important role in tumor, inflammation, immune system, vascular regulation, etc.." (PMID 34484174, 2021). "Siponimod (BAF312) is a selective antagonist of S1PR1, which inhibits tumor growth and angiogenesis in vitro by downregulating the S1PR1/P-STAT3/VEGFA axis." (PMID 34059068, 2021). "In contrast, SMYD3 knockdown significantly suppressed tumor growth and reduced tumor proliferation; these effects were largely reversed by S1PR1 overexpression." (PMID 34301921, 2021). "Lee H demonstrated that Stat3-induced S1PR1 expression, as well as S1P/S1PR1 pathway, is important for persistent Stat3 activation in cancer cells and the tumor microenvironment and for malignant progression." (PMID 32799825, 2020). "As shown in recently reports, endothelial loss of S1PR1 led to a reduction in CD45+ cells, macrophages, and DCs, which influences tumor growth and metastasis." (PMID 32799825, 2020). "Studies have shown that S1PR1 can affect the proliferation and differentiation of lymphocytes in the tumor microenvironment." (PMID 32799825, 2020). "Collectively, these results further demonstrated that miR-363 acts as a tumour suppressor of ccRCC in vivo by downregulating S1PR1 and blocking ERK-related pathways." (PMID 32536815, 2020). "Compared to normal tissues, S1PR1 mRNA expression was significantly decreased in primary tumors and tumor stages (stage 1, stage 2, stage 3, and stage 4) of BRCA, LUAD, and LUSC." (PMID 32799825, 2020). "miR-205 directly targeted S1PR1 to regulate SM and consequent cell proliferation and tumor development." (PMID 33101013, 2020). "We have recently uncovered that endothelial cell (EC) S1PR1 controls the effectiveness of VEGFR2 driven tumor angiogenesis." (PMID 32944615, 2020). "In line with our findings, previous studies demonstrated that the S1P/S1PR1 axis modulates the anti-tumor immune response." (PMID 31974367, 2020). "S1PR1 is usually considered as an oncogene, since it promotes the proliferation, invasion, and metastasis of tumor cells through the STAT3, PI3K/AKT, and CCR signaling pathway in many types of malignant tumors." (PMID 33628734, 2020). "CSO treatment repressed the expression of S1PR1 in cells and tumor tissues accompanied by the downregulated expression of cyclinD1 and upregulated expression of p27." (PMID 33101013, 2020). "Taken together, we showed that the VEGF-VEGFR2 pathway requires S1PR1-induced signaling in ECs to efficiently drive tumor vascularization and growth." (PMID 32944615, 2020). "Recent research has shown that S1PR1 signaling is an important vascular factor affecting tumor progression, metastasis, and responses to chemotherapy and immunotherapy." (PMID 32799825, 2020). "In another report, LPS/S1PR1 signaling participates in NLRP3 expression and IL-1β production in tumor-associated macrophages." (PMID 32695095, 2020). "CSO significantly down-regulated S1PR1 and Cyclin D1 expression and upregulated the expression level of p27 in tumor tissues and cells." (PMID 33101013, 2020). "More importantly, tumor cells with low S1PR1 expression receive nutrition through VM, and accelerate tumor growth in animal models." (PMID 32799825, 2020). "miR-363 downregulated S1PR1 expression and suppressed the proliferation, migration and invasion abilities of ccRCC cells in vitro and suppressed xenograft tumour growth in vivo." (PMID 32536815, 2020).
tumor (continued). "S1PR1 was a determinant of immune infiltration in BRCA (tumor purity; r = − 0.508, P = 1.76e-66), including subtypes of BRCA (BRCA-Basal: r = − 0.5411, P = 1.28e-06; BRCA-Her2: r = − 0.505, P = 4.44e-06 and BRCA-Luminal: r = − 0.557, P = 9.15e-46)." (PMID 32799825, 2020). "The Oncomine database was used to analyze S1PR1 mRNA levels in tumor tissues and normal tissues of various cancer types." (PMID 32799825, 2020). "MCL cells express high surface levels of S1PR1, and low S1PR1 expression contributes to retention within microenvironmental niches, likely promoting tumor cell survival." (PMID 32370190, 2020). "After adjusting for tumor purity, S1PR1 expression levels were significantly positively correlated with marker sets for various immune cells, except for NK cells, Th17, and T cell exhaustion in BRCA." (PMID 32799825, 2020). "We used the tumor cell supernatant to evaluate VEGF expression in MDA-MB-231 cells (overexpressing S1PR1 or control) and MCF-7 cells (transfected with the shControl or shS1PR1) through ELISAs." (PMID 30814488, 2019). "Collectively, these results indicated that activation of STAT3 was necessary for S1PR1 in promoting tumor cell proliferation and inhibiting tumor cell apoptosis." (PMID 31438989, 2019). "Tumor cells in the low S1PR1 group obtained nutrients through VM, and tumor growth was accelerated in animal models." (PMID 30814488, 2019). "S1PR1 is also highly expressed in endothelial cells and pericytes, and the expression of S1PR1 within these cells is important for tumor angiogenesis and metastasis." (PMID 31534132, 2019). "Taking this into consideration, it would be plausible to expect S1PR1 as a reciprocal regulator of the neovasculature, especially in light of our recent findings that, at least in tumor context, S1PR1 regulates lymphangiogenesis." (PMID 31357710, 2019). "S1PR1 is a G-protein-coupled receptor whose interaction with RhoA can regulate many functions of tumor cells, including cell growth, survival, migration, and morphogenesis." (PMID 30814488, 2019). "The tumor imposed depletion of Sphingosine-1-phosphate receptor 1 from the T cell surface prevents their trafficking from lymphoid organs into the circulation." (PMID 31114757, 2019). "Macrophage-specific deletion of S1PR1 in a mammary carcinoma model enhanced lung metastasis by inducing tumor lymphangiogenesis." (PMID 31379883, 2019). "Compared to the group only with S1PR1 expression interference, combination of S1PR1 knockdown and SH-4-54 induced a significant reduction in tumor growth." (PMID 31438989, 2019). "S1P causes the S1PR1-mediated activation of STAT3, and thereby accumulation of Treg in the tumor niche, as evidenced in an in vivo model of the B16 melanoma cell line, MB49 bladder carcinoma line, and in patients with breast cancer." (PMID 29467963, 2018). "S1PR1, one of the five G protein-coupled receptors for S1P, is crucial for the retention of lymphocytes of secondary lymphoid organs and tumor angiogenesis and metastasis." (PMID 30377291, 2018). "Most importantly, ERO1α knockdown significantly repressed the death of HCC xenograft mouse models by reducing tumor distant metastasis, and host angiogenesis by suppressing the expression of S1PR1, p-STAT3, and VEGF-A in HCC cells." (PMID 30377291, 2018). "Many genes account for several aspects of the endothelial response, such as VEGFA, IL6 and TYMP for tumor angiogenesis, and S1PR1 for development and cell differentiation." (PMID 29088816, 2017). "It has been demonstrated that S1PR1 is upregulated in tumor vessels and its local knockdown suppressed vascular stabilization and angiogenesis as well as tumor growth in implanted Lewis lung carcinoma cells." (PMID 28804221, 2017). "The genetic deletion of the S1PR1 in a subset of TAMs infiltrating murine PyMT breast tumors prevented pulmonary metastasis and drastically reduced tumor lymphangiogenesis." (PMID 28804221, 2017).
tumor (continued). "During embryonic development and tumor progression, the S1P/S1PR1 axis promotes endothelial precursor recruitment and vascular development." (PMID 27800303, 2016). "In malignant cells and immune cells, but also in tumour stromal components such as endothelial cells, the expression of S1PR1 is upregulated." (PMID 26501341, 2015). "Cases showing S1PR1 staining with an intensity similar to or stronger than reactive mantle B-cells in more than 30% of tumor cells were interpreted as being positive for S1PR1 expression." (PMID 25472725, 2014). "In DLBCLs, S1PR1 was stained in the cytoplasm of tumor cells with variable intensities and proportions." (PMID 25472725, 2014). "Indeed, targeting S1PR1 demonstrates significant potential in vitro and vivo for controlling tumor growth in this study." (PMID 41513624, 2026). "S1PR1 is a G protein-coupled receptor that plays a key role in regulating lymphocyte trafficking, immune response, cardiovascular system function, cell proliferation and survival, tumor angiogenesis, and metastasis." (PMID 41628231, 2026). "However, little research has studied the ECM on S1PR1 in the regulation of lymphatic endothelial cells (LECs) in tumor lymphangiogenesis." (PMID 39991586, 2025). "In this study, we showed that LMW-HA derived from tumor cells could induce S1PR1 translocation from the LECs surface to the endoplasmic reticulum (ER), leading to lymphangiogenesis promotion." (PMID 39991586, 2025). "Notably, the S1PR1 signalling is recognised as a therapeutically actionable target, with small-molecule modulators of S1PR1 showing potential to disrupt tumour-promoting signalling networks and overcome drug resistance in various cancers." (PMID 40807478, 2025). "In particular, the regulatory mechanisms of S1PR1 in tumor lymphangiogenesis remain elusive." (PMID 39991586, 2025). "Conversely, in cholangiocytes, S1pr1 was downregulated in pre-tumor and HCC groups." (PMID 40057751, 2025). "In summary, this paper demonstrated that tumor cells-derived LMW-HA could trigger S1PR1 endocytosis, which leads to lymphangiogenesis." (PMID 39991586, 2025). "In hepatocytes, S1PRs, especially S1pr1 and S1pr2, were only up-regulated in the pre-tumor group." (PMID 40057751, 2025). "Additionally, endothelial expression of S1PR1 influences tumor vascular integrity, affecting angiogenesis, tumor growth, and hematogenous metastasis." (PMID 40995371, 2025). "This study has unveiled a novel finding that tumor cell-derived LMW-HA-induced S1PR1 endocytosis could trigger lymphangiogenesis, in which LYVE-1-mediated enhancement of Src phosphorylation may be responsible for the underlying mechanism." (PMID 39991586, 2025). "Our analysis revealed that S1PR1 could negatively regulate these genes, suggesting that S1PR1 fulfills a tumor-suppressive role by inhibiting the ECM." (PMID 39551792, 2024). "One study showed that increased S1PR1 in CD4+ T-cells promotes STAT3 activation and JAK/STAT3-dependent Treg tumor migration, while ablation of STAT3 in T-cells reduces tumor-associated Treg accumulation and tumor migration." (PMID 38542328, 2024). "The administration of S1PR1 inhibitors could enhance the phagocytosis of tumor cells and improve outcomes for patients." (PMID 38339325, 2024). "In the context of cancer, S1PR1 is known to reduce tumor angiogenesis." (PMID 36835432, 2023). "Targeting FLNB to regulate S1PR1 localization may provide additional therapeutic interventions for treating vascular inflammation and related vascular diseases as well as tumor angiogenesis." (PMID 37220855, 2023). "S1PR1 signaling stimulates cancer cell growth and angiogenesis and promotes tumor cell metastasis." (PMID 37828220, 2023). "Another related GPCR, S1PR1, is also targeted by miR-145-5p, a tumor suppressor reported in DLBCL." (PMID 36672402, 2023). "However, in the tumor microenvironment, S1PR1 promotes cancer progression by enhancing tumor vascularization and reducing hypoxia." (PMID 37220855, 2023).
tumor (continued). "While these properties of S1PR1 signaling remain to be specifically addressed in tumor models, they indicate that S1PR1-dependent signaling may combine favoring tumor-promoting inflammation with suppressing anti-tumor immunity." (PMID 35163211, 2022). "Taken together, S1PR1 is an important regulator of immune cell migration also during cancer progression, while at the same time influencing survival, proliferation and pro-tumor cytokine secretion of tumor infiltrating leukocytes." (PMID 35163211, 2022). "Furthermore, this thymocyte accumulation in the bone marrow was reversed when S1PR1 internalization was blocked, resulting in more tumor-infiltrating leukocytes and enhanced survival." (PMID 36160839, 2022). "In addition, the caerin gel treatment recruits almost two-fold more activated CD8+ T cells to the TME, relative to the untreated tumour, which shows a synergistic effect derived from the regulation of S1pr1, Ccr7, Ms4a4b and Gimap family expression." (PMID 34858827, 2021). "Besides, high expression of S1PR1 was correlated with a shorter time to tumor recurrence in BRCA patients." (PMID 34059068, 2021). "Interestingly, the tumor vessels of endothelial specific s1pr1 knockout mice have decreased endothelial barrier function and increased vascular sprouting and branching, while the overexpression of S1PR1 leads to the opposite phenotype." (PMID 33924941, 2021). "In view of the important role of S1PR1 in the occurrence, development and metastasis of tumors, noninvasive monitoring of the expression of S1PR1 in malignant tumors has important clinical significance in formulating tumor treatment plans, monitoring treatment effects, and evaluating prognosis." (PMID 34484174, 2021). "In addition, the S1PR1 antagonist BAF312 effectively inhibited tumor growth and decreased angiogenesis by affecting S1PR1/P-STAT3/VEGFA signaling." (PMID 34059068, 2021). "All these findings suggested that S1PR1 affects tumor growth by affecting P-STAT3/VEGFA signaling." (PMID 34059068, 2021). "Analysis of clinical gene expression data suggests that endothelial or immune cells in tumor tissue may be the source of S1PR1 expression." (PMID 34503284, 2021). "FTY720 (Fingolimod/Gilenya, Novartis, Basel, Switzerland) is a sphingosine analogue drug that is phosphorylated by SphK2 to produce a structural analogue of S1P and functional antagonist for S1PR1 that acts a tumor suppressor in colon and lung cancer cell lines and mouse models." (PMID 34069611, 2021). "In addition, research has reported that S1PR1 activity increases tumor growth by amplifying VEGFA angiogenic signaling." (PMID 34059068, 2021). "Aberrant S1PR1/P-STAT3 signaling loops have been detected in various tumor types." (PMID 34059068, 2021). "Moreover, knockdown of S1PR1 repressed the proliferation and enhanced the apoptosis of ESCC cells, indicating a pro-tumor effect of S1PR1 in ESCC." (PMID 34831211, 2021). "Comparison of tumor associated ECs with and without S1PR1 showed impaired angiogenic signaling in the S1PR1 null ECs." (PMID 34690821, 2021). "Results confirmed BAF312@cRGD-CaP-NP could dramatically inhibit tumor growth and angiogenesis in vitro and in MDA-MB-231 tumor-bearing mice via downregulating the S1PR1/P-STAT3/VEGFA axis." (PMID 34059068, 2021). "Although it is known that inhibition of S1PR1 has multiple mechanisms to counteract tumor growth, the resulting risk of metastasis should not be overlooked." (PMID 34503284, 2021). "Previous studies have indicated that S1PR1 plays a pivotal role in several tumours." (PMID 32536815, 2020). "Furthermore, we studied the correlation between S1PR1 and tumor-infiltrated immune cells in the tumor microenvironment using TIMER." (PMID 32799825, 2020). "However, some recent studies revealed that S1PR1 is also able to promote tumor cell apoptosis, thus, its high expression is an indicator of a good prognosis." (PMID 33628734, 2020).